WEE1 (WEE1 G2 checkpoint kinase)
Diseases named in the same sentence as WEE1 in open-access papers (continued):
Sharing a sentence is not in itself a finding about the gene and the disease.
triple-negative breast carcinoma (18 papers, 2015 to 2025). An invasive breast carcinoma which is negative for expression of estrogen receptor (ER), progesterone receptor (PR), and human epidermal growth factor receptor 2 (HER2). "Recent studies have identified WEE1 as a potential therapeutic target in several cancers, including therapy-resistant triple-negative breast cancer." (PMID 40565165, 2025). "Nonetheless, our findings are consistent with previous studies demonstrating that loss of PTEN and activation of AKT leads to reduced nuclear localization and impaired CHK1 function and lethal interactions between inhibition of CHK1 and WEE1 in triple-negative breast cancers (TNBCs)." (PMID 32628111, 2020). "This comment extends a recent Advanced Science paper by reporting higher WEE1‐dependency of triple negative breast cancer (TNBC) cell lines, pejorative prognostic value of WEE1 expression in TNBC clinical samples as well as higher expression of biomarkers of sensitivity to WEE1 inhibitor." (PMID 34227743, 2021).
malaria (17 papers, 2010 to 2023). Malaria is a serious and sometimes fatal disease caused by a parasite that commonly infects a certain type of mosquito which feeds on humans. "Interestingly, in malaria parasites there are no candidates for Polo-like kinases, neither are there strong candidates for the network of proteins regulating the activation of the cyclin B–Cdk1 complex such as the mitotic cyclin-CDK inhibitory kinases Wee1 and Myt1 and the Cdc25 phosphatase." (PMID 21166904, 2011).
atherosclerosis (14 papers, 2014 to 2025). A disease characterized by the build-up of fatty material and calcium deposition in the arterial wall resulting in partial or complete occlusion of the arterial lumen. "Either macrophage WEE1 deficiency or inactivation significantly prevented atherosclerosis by reducing macrophage inflammation." (PMID 40202104, 2025). "WEE1MCKO mice, as well as the littermate WEE1f/f mice, were constructed to investigate the role of macrophage WEE1 in atherosclerosis." (PMID 40202104, 2025). "The purpose of this study was to clarify the regulatory role and mechanism of WEE1 in atherosclerosis." (PMID 40202104, 2025). "Considering that the phosphorylating change of WEE1 appears bigger than that of SGK1 and SGK1 has been reported to play a pivotal role in the development of atherosclerosis, we selected WEE1 for further investigation." (PMID 40202104, 2025). "The findings demonstrate that macrophage WEE1 drives NF‐κB activation and atherosclerosis by directly phosphorylating p65 at S536." (PMID 40202104, 2025). "To investigate the role of macrophage WEE1 in atherosclerosis, we utilized transcriptome sequencing in oxLDL‐stimulated MPMs from the macrophage‐specific WEE1 knockout (WEE1MCKO) and littermate WEE1f/f mice." (PMID 40202104, 2025). "Macrophage‐specific deletion of WEE1 or pharmacological inhibition of WEE1 kinase activity attenuates atherosclerosis by reducing inflammation in mice." (PMID 40202104, 2025). "Our study illustrates a macrophage‐specific WEE1‐p65 axis in regulating atherosclerosis and indicates WEE1 as a pharmacological target for atherosclerosis." (PMID 40202104, 2025). "This study identifies WEE1 as a new upstream kinase of p65 and a potential therapeutic target for atherosclerosis." (PMID 40202104, 2025). "We then evaluated the role of macrophage WEE1 in atherosclerosis both in vivo and in vitro." (PMID 40202104, 2025). "Although the upstream mechanism for WEE1 activation in atherosclerosis needs to be further investigated, our findings point out new directions to broaden the clinical applications for WEE1 inhibitor MK1775 in cardiovascular diseases and even other inflammatory diseases." (PMID 40202104, 2025). "Thus, the in vivo data suggest that WEE1 phosphorylation at S642 is involved in atherosclerosis." (PMID 40202104, 2025). "Here, a protein kinase, WEE1 G2 checkpoint kinase (WEE1), promoting inflammation in atherosclerosis is identified." (PMID 40202104, 2025). "We showed that macrophage WEE1 phosphorylation, but not protein level, positively correlated with high‐fat diet (HFD)‐induced atherosclerosis." (PMID 40202104, 2025).
schizophrenia (14 papers, 2009 to 2026). A major psychotic disorder characterized by abnormalities in the perception or expression of reality. "Both WEE1 and FGF14 have been associated with schizophrenia and other neurodevelopmental disorders." (PMID 39125637, 2024). "Thus, WEE1 may be part of a signaling pathway, including FGF14 and Nav1.2, that, if perturbed, could contribute to endophenotypes related to neurodevelopmental disorders such as schizophrenia and SCN2A channelopathies associated with autism spectrum disorder and epilepsy." (PMID 39125637, 2024).
cervical carcinoma (13 papers, 2016 to 2025). A carcinoma arising from either the exocervical squamous epithelium or the endocervical glandular epithelium. "We investigated the effects of combined treatment of Wee1 inhibitor with IR on apoptosis in cervical cancer cells by annexin V immunostaining and FACS analysis." (PMID 31659268, 2019). "This study was designed to investigate the preclinical efficacy of the combination therapy of the Wee1 inhibitor and IR in cervical cancer models." (PMID 31659268, 2019). "In this study, we showed that the inhibition of Wee1 by AZD1775 significantly increased the efficacy of RT by acting as a radiosensitizer in cervical cancer models." (PMID 31659268, 2019). "Furthermore, using the panel of cervical cancer cell lines, we determined that FBXW7-mutant cells (C33A) were more susceptible to CHK1 and WEE1 inhibition than FBXW7 wild-type lines." (PMID 38032106, 2023). "We also investigated the association between pWee1 and pChk1 in order to provide clues on whether Wee1 activation in cervical cancer is mediated by Chk1." (PMID 26930412, 2016). "Our data show for the first time that Wee1 inhibition by AZD1775 abrogates the prolonged the G2 checkpoint induced by RT and leads to dramatic radiosensitization in cervical cancer." (PMID 31659268, 2019). "In this study, we investigated the effects of a combination of Wee1 inhibitor (AZD1775) and irradiation in cervical cancer." (PMID 31659268, 2019). "Cervical cancer cell lines showed lower intensities of Wee1 expression as opposed to placental trophoblastic cells." (PMID 31659268, 2019).
lymphoma (13 papers, 2013 to 2025). A malignant (clonal) proliferation of B- lymphocytes or T- lymphocytes which involves the lymph nodes, bone marrow and/or extranodal sites. "Meanwhile, RRM2 inhibition acted in synergy with gemcitabine in lymphoma and with a WEE1 inhibitor in H3K36me3-deficient cancers." (PMID 36315425, 2022). "Here, combined PDS and WEE1 inhibitor exposure dramatically increases chromosomal instability compared to PDS alone in CH12 lymphoma cells, suggesting potential synergy of G4 ligands with drugs targeting cell cycle checkpoints." (PMID 40833407, 2025). "DNA-damaged lymphoma cells exhibit high levels of Wee1-dependent phosphorylated Y15 CDK1, preventing progression from the G2 to the M phase." (PMID 39501277, 2024). "Using a Wee1 inhibitor to break through the G2/M checkpoint can induce massive cell death in chemotherapy-treated lymphoma." (PMID 39501277, 2024). "In conclusion, MCL cell lines are considerably more sensitive to Chk1 and Wee1 inhibitors as single agents than other lymphoma cell lines and epithelial tumor cell lines." (PMID 25428911, 2015). "MCL were the lymphoma cell lines most sensitive to Chk1 and to a lesser extent to Wee1 inhibition." (PMID 25428911, 2015). "Little is known about the putative role and effects of Chk1 and Wee1 inhibitors in lymphomas." (PMID 25428911, 2015). "Our data clearly showed that, among all the lymphoma cell lines, MCL cell lines are significantly more sensitive to the Chk1 inhibitor PF-00477736 and, even though to a lesser extent, more sensitive to the Wee1 inhibitor MK-1775." (PMID 25428911, 2015).
head and neck cancer (12 papers, 2017 to 2025). A primary or metastatic malignant neoplasm affecting the head and neck. "Further, they are consistent with synergistic effects between Aurora A, the upstream kinase activating Plk1, and Wee1 inhibition in head and neck cancer models." (PMID 40256327, 2025). "Validating these findings in human models, WEE1 kinase inhibition sensitized two human head and neck cancer cell lines to direct lysis by haNK cells." (PMID 29925431, 2018). "So far namely, to our knowledge using PARP and WEE1 inhibitors in combination for oropharyngeal or head and neck cancer has still not been pursued, despite positive effects for other cancers, as shown and reviewed by others." (PMID 35891353, 2022).
liver cancer (12 papers, 2014 to 2024). An epithelial or non-epithelial malignant neoplasm that arises from the liver. "Our findings establish anti-apoptotic roles of the master clock regulators BMAL1 and CLOCK in promoting proliferation of liver cancer cells and reveal an underpinning mechanism being mediated by the cancer-state essential gene Wee1." (PMID 36595671, 2023). "In the liver cancer, DLX6-AS1 could enhance WEE1 expression via targeting miR-424-5p to aggregate the liver cancer progression; in addition, DLX6-AS1 promoted liver cancer carcinogenesis via targeting the miR-203a/matrix metalloproteinase-2 axis." (PMID 31787849, 2019). "Using TargetScan and miRanda database, we found that the potential predicated target genes of miR-646 consist of methylthioadenosine phosphorylase (MTAP), WEE1 G2 checkpoint kinase (WEE1), and cyclin D2 (CCND2), which are involved in the development of liver cancer." (PMID 25177719, 2014).
multiple myeloma (12 papers, 2013 to 2026). "A recent study also showed that combined bortezomib and WEE1 inhibitor (MK1775) achieved a synergistic effect in multiple myeloma and depleting stem-like cells in multiple myeloma." (PMID 37834095, 2023). "Both CHK1 and WEE1 were significantly overexpressed in human myeloma cell lines (HMCLs, n= 42) compared to normal bone marrow plasma cells (BMPCs, n=5) (p<0.001 and p<0.001 respectively)." (PMID 38125947, 2023). "Inhibiting DDR components, like PARP, ATR, WEE1, CHK1/2, ATM, and DNA-PKs, is under evaluation in early-phase studies for multiple myeloma and other hematological malignancies showing promising preliminary signals of activity." (PMID 41155462, 2025). "Here, we report that bortezomib (BTZ), a proteasome inhibitor that has been used to treat plasma cell myeloma, induced G2/M phase cycle arrest in the MDS cell line SKM-1 through upregulation of Wee1, a negative regulator of G2/M phase transition." (PMID 24608798, 2014). "In other work, human multiple myeloma (MM) cells were treated with MEDI2228, a ligand of the B-cell maturation antigens that induces ATM/ATR-Chk1/2 pathway activation, in combination with different inhibitors of the principal kinases of the DDR (ATM, ATR, and WEE1)." (PMID 37655260, 2023).
acute lymphoblastic leukemia (11 papers, 2014 to 2024). Leukemia with an acute onset, characterized by the presence of lymphoblasts in the bone marrow and the peripheral blood. "Our studies revealed that ISAE induces G2/M arrest in the T cell acute lymphoblastic leukemia cell line—Jurkat cells, and stimulates the ATR/CHK1/Wee1/CDC25C signaling pathway." (PMID 38195460, 2024). "Of note, we proved that Wee1 genetic depletion substantially delayed mitotic exit and that chemically inhibiting Wee1 with AZD-1775 synergized with MTAs by further prolonging mitosis and increasing cell death in cancer cell lines and primary human lymphoblastic leukemia cells." (PMID 32398657, 2020). "Reports show that T‐cell acute lymphoblastic leukemia (T‐ALL) cell lines and xenografts are sensitive to inhibitors of ATR, CHK1, and Wee1." (PMID 35510955, 2022). "However, WEE1 inhibition has not been well studied as a target for acute lymphoblastic leukemia, nor in combination with other, commonly used, conventional chemotherapeutics for ALL." (PMID 26334102, 2015).
endometrial cancer (11 papers, 2018 to 2025). Primary or metastatic malignant neoplasm involving the endometrium (mucous membrane that lines the endometrial cavity). "Consistently, our study revealed that overexpression of WEE1 protein was statistically linked with unfavorable prognosis in endometrial cancer patients." (PMID 38169513, 2024). "Our study revealed that the expression levels of the WEE1 protein were significantly higher in tumor tissues of patients with recurrent endometrial cancer, and were associated with clinical prognosis." (PMID 38169513, 2024). "To delineate the mechanisms underlying the impact of WEE1 inhibitors on endometrial cancer, we treated HEC-1-A, HEC-1-B, ISHIKAWA, RL95-2, and KLE cell lines with different concentrations of AZD1775 for 72 h." (PMID 38169513, 2024). "The Wee1 gene is scarcely mutated in solid tumors, and about 3.2% of endometrial cancers are characterized by Wee1 point mutations." (PMID 37109350, 2023). "We aimed to examine if WEE1 inhibition could elicit anti-tumor effects and its underlying mechanisms, with the hope of introducing a novel postoperative treatment strategy for endometrial cancer patients, particularly those experiencing recurrence." (PMID 38169513, 2024). "Hence, in this study, we aim to delve into the anti-tumor effects of WEE1 inhibitors and associated mechanisms in endometrial cancer comprehensively, in hopes of offering a viable treatment for patients with endometrial cancer, particularly those prone to relapse and metastasis." (PMID 38169513, 2024). "WEE1 inhibitors effectively eliminated endometrial cancer cells while inhibiting their proliferation and migration." (PMID 38169513, 2024). "In this study, in vitro experiments demonstrated WEE1 protein is expressed in the cancer tissues of endometrial cancer patients." (PMID 38169513, 2024). "In examining the impact of WEE1 inhibitors on endometrial cancer progression, we conducted clone formation, wound healing, and transwell assays." (PMID 38169513, 2024). "A series of in vitro and in vivo experiments confirmed the potent antitumor effects of WEE1 inhibitors on endometrial cancer, which appeared to be related to the activation of the innate immune response." (PMID 38169513, 2024). "This research investigates the anti-tumoral capacities of WEE1 inhibitors within the context of endometrial cancer, aiming to establish a novel therapeutic avenue for high recurrence-risk patients." (PMID 38169513, 2024). "qRT-PCR and western blotting elucidated that WEE1 inhibitors activated the innate immune signaling pathway in endometrial cancer cells." (PMID 38169513, 2024). "This research underscores the significant potential of WEE1 inhibitors in the therapeutic arsenal against endometrial cancer, particularly for patients with recurrent disease and poor prognosis." (PMID 38169513, 2024). "Materials and methods: We evaluated WEE1 expression in endometrial cancer patients utilizing immunohistochemistry on paraffin-embedded tissue sections." (PMID 38169513, 2024). "Our findings showed high WEE1 kinase expression in endometrial cancer tissue, with significant higher expression level of WEE1 protein in recurrent patients (P<0.0001)." (PMID 38169513, 2024). "Next, we analyzed the synergism of EphA2 and Wee1 inhibition in two endometrial cancer cell lines (Hec1A and Ishikawa) known to have high expression levels of EphA2." (PMID 36835335, 2023). "In conclusion, EphA2- and Wee1-targeted therapies show synergistic interaction in endometrial cancer in both in vitro and in vivo experiments." (PMID 36835335, 2023).